MARCO (macrophage receptor with collagenous structure)
Diseases named in the same sentence as MARCO in open-access papers (continued):
Sharing a sentence is not in itself a finding about the gene and the disease.
tumor (140 papers, 2013 to 2026). "TCGA analysis indicated that MARCO expression is significantly altered in most tumor tissues compared to normal tissues and is associated with the infiltration of multiple immune cell types, with a particularly strong correlation to macrophage abundance." (PMID 41766903, 2026). "Employing transcriptomic, spatial proteomic and histological analyses of human samples, MARCO was found on a specific subtype of tumor-associated macrophages linked to immunosuppression and extracellular matrix remodeling within the tumor microenvironment." (PMID 42049706, 2026). "By contrast, ICC’s “MARCO+ tumor-associated macrophage (TAM)” pattern is accompanied by JCHAIN downregulation and suppresses T-cell infiltration." (PMID 41153653, 2025). "Here, an immunosuppressive ecosystem in ICB‐resistant tumors is identified, featured by preferential infiltration of MARCO+ tumor‐associated macrophages (TAMs) and restrained cytotoxicity of CD8+ cytotoxic T lymphocytes (CTLs)." (PMID 41117057, 2025). "The macrophage receptor with collagenous structure (MARCO), a member of the class A scavenger receptor family, has recently been revealed as an important immunomodulator in tumor-associated macrophages (TAMs), particularly within the M2-like sub-population." (PMID 40695812, 2025). "Macrophages_LYVE1 also expressed high levels of LYVE1, RNASE1, STAB1, CD163, and MARCO, which are associated with macrophage function and tumour immunosuppression." (PMID 40759637, 2025). "We observed that immune responders had higher expressions of MARCO, a gene expressing a pattern recognition receptor on tumor-associated macrophages." (PMID 41301877, 2025). "In vivo studies using MARCO deficiency mice demonstrated significant tumor growth suppression that was associated with marked reduction of intratumoral M-MDSCs and M2-like TAMs, and enhanced accumulation of CD8+ T cells and NK cells." (PMID 40695812, 2025). "The downregulation of IL-1β and NF-κB inhibitor in MARCO deficiency further suggests the disruption of pro-inflammatory signaling pathways that typically sustain tumor-promoting chronic inflammation." (PMID 40695812, 2025). "The results indicated that MARCO deficiency reduced the tumor-infiltrated M-MDSCs with the increase of G-MDSCs." (PMID 40695812, 2025). "The macrophage receptor with collagenous structure (MARCO), found on tumor-associated macrophages (TAMs), has been shown to stimulate Treg proliferation and IL-10 production in NSCLC." (PMID 41378295, 2025). "The scavenger receptor MARCO (macrophage receptor with collagenous structure), a class A scavenger receptor, is primarily expressed on macrophages including tumour-associated macrophages, and lung macrophages." (PMID 40093086, 2025). "Collectively, these data indicate that MARCO deficiency prevents tumor growth by inhibiting tumor-infiltrated MDSCs and TAMs and increasing CD8+ T cells and NK cells." (PMID 40695812, 2025). "In several cancer model experiments, the high expression of MARCO has been shown to promote lipid accumulation confers protumor features to tumor-associated macrophages." (PMID 39795974, 2024). "The most significantly upregulated gene at time of PD was MARCO, which is associated with M2 tumor associated macrophages (TAMs) and has been shown to be upregulated in human DLBCL TAMs." (PMID 37624862, 2023). "A tumor-specific splicing variant of macrophage receptor with collagenous structure (MARCO) promotes metabolic dysregulation resulting in a hypoxic tumor microenvironment by regulating the HIF-1α signaling." (PMID 37845393, 2023). "MARCO expression was found to be associated with the expression of M2 markers defined as being expressed by macrophages that promote tumor growth." (PMID 37426676, 2023). "Herein we report that a high prevalence of MARCO+ myeloid cells in the tumor area is associated with exclusion of NK and T cells in PDAC." (PMID 36310582, 2022).
tumor (continued). "We have demonstrated that MARCO+ macrophage presence in the TME of PDAC is associated with a lymphocyte-excluding tumor phenotype." (PMID 36310582, 2022). "They included three immune cell populations: a promyelocyte population, a tumor-associated macrophage (TAM) population expressing low levels of MARCO, and a basophil cluster." (PMID 36008377, 2022). "Anti-human MARCO (anti-hMARCO) antibody targeting triggered the repolarization of tumor-associated macrophages and activated the inflammasome machinery, resulting in IL-18 production." (PMID 36310582, 2022). "Meanwhile, the upregulation of glycolysis and hypoxia gene sets is consistent with the enrichment of MARCO+ macrophages in the tumor core—which is known to be associated with pro-tumor macrophages." (PMID 34011400, 2021). "Our findings of the pro-tumor TAM traits associated with MARCO in GBM adds credence to its importance across cancers." (PMID 34011400, 2021). "Expression of MARCO has been used to define a population of suppressive tumor-associated macrophages." (PMID 32228601, 2020). "Macrophage receptor (MARCO), a scavenger receptor is expressed by suppressive tumour-associated macrophages (TAM) called M2 macrophages." (PMID 31467500, 2019). "The expression of MARCO in the tumor microenvironment has been linked to poorer outcomes in human breast cancer." (PMID 30348985, 2018). "In I-type tumours, high MARCO+ density was significantly associated with a reduced OS in patients who received adjuvant chemotherapy (p = 0.021), but not in patients who did not receive adjuvant chemotherapy." (PMID 28673320, 2017). "In I-type tumours, however, high MARCO+ density was significantly associated with a reduced OS (p = 0.038)." (PMID 28673320, 2017). "The current study has shown that loss of expression of the scavenger receptor MARCO enhances the trafficking and anti-tumor efficacy of DCs pulsed with tumor lysates." (PMID 23840879, 2013). "Exposure of murine tumor lysate-pulsed DCs to an anti-MARCO antibody led to loss of dendritic-like processes and enhanced migratory capacity." (PMID 23840879, 2013). "Anti-MARCO antibody linked to tumor lysate-pulsed DCs enhance, tumor-reactive IFN-gamma producing T cells and reduced tumor growth in mice." (PMID 24228179, 2013). "We performed additional studies in which mice were vaccinated with tumor lysate-pulsed DC generated from the bone marrow of mice deficient in both MARCO and SRA." (PMID 23840879, 2013). "MARCO expression on macrophages has also been linked to tumour development." (PMID 40565155, 2025). "Furthermore, MARCO deficiency prevented tumor growth and was associated with significant changes in MDSCs." (PMID 40695812, 2025). "Notably, murine and human tumor-associated macrophages (TAMs) show elevated MARCO expression, potentially linked causally to their increased lipid accumulation." (PMID 39795974, 2024). "For example, the targeting of TREM2, SPP1 and MARCO is currently under extensive investigation, and the first in vivo studies demonstrated promising results associated with the inhibition of immunosuppression and further decreased tumor growth." (PMID 39516356, 2024). "Subset analysis revealed that tumor-associated macrophages are the only cell type that exhibits transcriptomic differences, compared to the nontumor counterparts, characterized by attenuated expression of the scavenger receptor MARCO (MARCOlow) in tumor macrophages." (PMID 40684183, 2025). "MARCO, upregulated in response to pathogenic challenge, has been implicated in defence against pathogens in the lung, phagocytosis and clearance of tumour cells, internalisation of exosomes, and has been touted as a potential target in anti-cancer immunotherapy." (PMID 41439503, 2025). "MARCO expression and immune cell infiltration were further analyzed using transcriptomic data from 33 tumor types in The Cancer Genome Atlas (TCGA)." (PMID 41766903, 2026).
tumor (continued). "This study identifies MARCO as a key regulator of immunosuppression, fibrosis and tumor progression in iCCA, and supports its potential as a novel therapeutic target for macrophage-directed immunotherapy." (PMID 42049706, 2026). "Therapeutic targeting of MARCO has also been proposed to enhance anti-tumor immune activity in several solid tumors." (PMID 39811671, 2025). "The expression of SIRPA, LILRB1, LILRB2, Siglec1, Siglec7, Siglec9, PDCD1, CD163 and MARCO are preferentially expressed on Mono01, Mono02 and Macro03, suggesting their tumor-promoting roles." (PMID 40755770, 2025). "On one hand, primary CRC tumors harbor MHC-low TAMs with impaired antigen presentation, liver metastases are enriched with THBS1+ MHC-low TAMs that express pro-angiogenic factors and genes like THBS1 and MARCO, supporting tumor progression." (PMID 41450739, 2025). "And the evaluation of M-MDSCs was more pronounced in the TDE group than in the tumor supernatant group, implicating that TDEs induce MARCO upregulation and M-MDSC differentiation." (PMID 40695812, 2025). "MARCO blockade significantly boosts ICB's benefits in in vivo models by recovering immune recognition of tumor cells and enhancing CD8+ CTL infiltration and effector function." (PMID 41117057, 2025). "Strikingly, combining the MARCO down-regulating antibody with PD-1 blockade synergistically enhanced anti-tumor efficacy." (PMID 40695812, 2025). "MHC‐I blockade considerably attenuated tumor growth inhibition brought on by MARCO knockdown in in vivo models." (PMID 41117057, 2025). "To assess the anti‐tumor efficacy of MARCO blockade in human RCC, we also established a patient‐derived xenograft (PDX) model." (PMID 41117057, 2025). "Spatial transcriptomics revealed the co-localization of MARCO+ TAMs with cathepsin E (CTSE+) tumor cells." (PMID 40507339, 2025). "Subsequent subclustering of CD68+CD206+MARCO+ AMs identified eight distinct clusters present across both normal and tumor tissue." (PMID 41567211, 2025). "A significant increase in the proportion of tumor-infiltrated CD8+ T and NK cells was observed in the MARCO deficiency group." (PMID 40695812, 2025). "No significant changes in the population of neutrophils (CD45+CD3‐CD11b+Ly6G+), B cells (CD45+CD3‐CD19+) or Tregs (CD45+CD3+CD4+FOXP3+) were observed in the tumor TME following anti‐MARCO treatment or its combination with PD‐1 mAbs." (PMID 41117057, 2025). "In lung cancer, tumor-derived IL37 promotes the generation of MARCO-positive TAMs, which contribute to an immunosuppressive environment." (PMID 41019045, 2025). "We subsequently demonstrated that tumor-derived exosomes (TDEs) induce MDSC differentiation accompanied by elevated MARCO expression and enhanced immunosuppression." (PMID 40695812, 2025). "In preclinical breast cancer models, anti-MARCO treatment also reduces tumour burden and metastatic dissemination." (PMID 40948757, 2025). "Exactly, failed ICB therapy elicited higher surface MARCO on TAMs, which contributes to a trending increase of MARCO+ TAMs, highlighting the potential role of MARCO and MARCO+ TAMs in immune inhibition and tumor growth promotion." (PMID 41117057, 2025). "Macrophages expressing the scavenger receptor MARCO, which contributes to their transformation into immunosuppressive TAMs, display a pro-tumor, anti-inflammatory phenotype." (PMID 41019045, 2025). "In vivo, MARCO down-regulating antibody suppressed tumor growth and reprogrammed the TME by diminishing immunosuppressive MDSCs and TAMs and revitalizing CD8+ T cells and NK cells." (PMID 40695812, 2025). "In models of breast and colon carcinoma as well as melanoma, an anti-MARCO monoclonal antibody has been developed and has exhibited anti-tumor effects in some cases through reprogramming TAMs to pro-inflammatory phenotypes and enhancing tumor immune responses." (PMID 40083710, 2025).
tumor (continued). "Our findings are consistent with prior studies that demonstrated MARCO blockade improved an anti‐tumor effect mediated by anti‐PD‐1 therapy." (PMID 41117057, 2025). "In fact, the macrophages in tumor cell nests co-express PD-L1 and MARCO, and a recent study demonstrated MARCO-expressing TAMs to suppress T and NK cell activity." (PMID 38245882, 2024). "Targeting lipid accumulation through MARCO blockade not only hinders tumor growth and invasiveness but also enhances the efficacy of chemotherapy in these cancer models." (PMID 39795974, 2024). "Inhibition of MARCO can reverse the immunosuppressive effects of TAMs, which in turn has been shown to reduce tumor progression in murine models of solid tumors." (PMID 38533720, 2024). "The utilization of MARCO-targeted antibodies induces the repolarization of TAMs, improves the level of IL-18, and strengthens the function of anti-tumor cells." (PMID 38590651, 2024). "Macrophage receptor with collagenous structure (MARCO) is a scavenger receptor expressed almost exclusively on tumor-promoting TAMs and are thought to have an immunoregulatory role within the TME supporting tumor growth." (PMID 38533720, 2024). "MARCO-expressing TAMs were shown to accumulate in NSCLC tissue, to be associated with pro-tumorigenic activity, and to counteract the activity and tumor cell-killing ability of cytotoxic T cells and NK cells in culture." (PMID 38942020, 2024). "MARCO targeting has been successful in animal models, where anti-MARCO antibodies block tumor growth and metastasis." (PMID 39516356, 2024). "Other genes mentioned in this study, such as macrophage-specific MARCO, surely represent immune cells in the tumor microenvironment." (PMID 37624862, 2023). "Administration of anti-MARCO antibody induces repolarization of TAMs and suppresses tumour growth in mouse models of solid tumours." (PMID 37313600, 2023). "The scavenger receptor MARCO expressed on the surface of macrophages is able to regulate macrophage polarization and enhance tumor killing." (PMID 36742323, 2023). "Ligands for MARCO include environmental particles, nucleic acids, bacterial lipopolysaccharides, viruses, oxidized lipoproteins, modified endogenous proteins, tumor cells, and dead cells or debris (43, –, 47)." (PMID 37078873, 2023). "Targeting scavenger receptor MARCO alters macrophage polarization and activates NK cells in the tumor." (PMID 37766594, 2023). "An anti-MARCO monoclonal antibody has been shown to boost tumor immunogenicity in melanoma models, reprogram TAM populations to a pro-inflammatory phenotype, and induce antitumor action in breast and colon carcinoma in preclinical studies." (PMID 37426676, 2023). "An anti-MARCO (A pattern recognition scavenger receptor) induces anti-tumor activity in multiple tumor models by reprogramming the TAMs population into a pro-inflammatory phenotype and increasing tumor immunogenicity." (PMID 36941614, 2023). "Using MARCO as a discriminative marker for resident KCs in humans, we found that KCs were enriched in tumor-distant liver tissues, but were scarce in the tumor core and periphery." (PMID 36821387, 2023). "The MARCO, CD14, FCGR3A, and CD163 genes, which are unique to tumor-associated macrophages (TAMs), were expressed in cluster two." (PMID 38096229, 2023). "In a mouse melanoma model, TAMs reprogrammed by anti-MARCO antibody activate NK cells to kill tumour cells via TRAIL." (PMID 37313600, 2023). "MARCO expression is considered to define a M2-like macrophage subtype with an immunosuppressive gene signature which is expressed by tumor-promoting macrophages producing a worse prognosis." (PMID 37153595, 2023). "And targeting MARCO on macrophages within the tumor alters their polarization and in turn activate NK cells to kill the tumor." (PMID 37158921, 2023). "CD209 (DC-SIGN), MARCO, and RELN genes function in the downregulation of the immune system through IL10 and inhibitory tumor-associated macrophage mechanisms, respectively." (PMID 34349241, 2022).
tumor (continued). "TAMs expressing MARCO blocked the activation of cytotoxic T cells and NK cells, inhibiting their proliferation, cytokine production, and ability to kill tumor cells." (PMID 36510315, 2022). "Antibodies targeting MARCO in NSCLC restore the anti-tumor activity of T cells and NK cells by polarizing suppressor macrophages." (PMID 35962453, 2022). "Targeting MARCO in these cultures markedly increased NK cell migration toward 2D tumor cells and into 3D tumor spheroids and improved anti-tumor activity." (PMID 36310582, 2022). "Quantification of PDAC tumor specimens revealed a decrease in T and NK cell numbers in the presence of MARCO+ macrophage infiltration and higher immune effector infiltration in MARCO− regions." (PMID 36310582, 2022). "High expression of the scavenger receptor named macrophage receptor with collagenous structure (MARCO) by suppressive TAMs promotes tumor growth and metastasis." (PMID 34914196, 2022). "Increased tumor-derived IL-10 also correlated with higher MARCO expression in TCMs, and this was reversed by neutralizing antibodies to IL-10." (PMID 36310582, 2022). "The anti-tumor activity of anti-MARCO is dependent on the binding of the Fc subunit with its inhibitory Fc receptor, FcγRIIB, similar to anti-CD40 antibody-mediated reprogramming." (PMID 35978372, 2022). "The TME was altered, featuring more pro-inflammatory macrophages, and treatment with anti-MARCO not only led to tumor shrinkage but also augmented the effects of anti-CTLA-4 immunotherapy through an NK cell-dependent mechanism." (PMID 36211808, 2022). "This suggests that the presence of MARCO+ myeloid cells can be a measure of a lymphocyte-excluded tumor, sometimes described as a ‘cold tumor phenotype’." (PMID 36310582, 2022). "The downregulation of the macrophage receptor MARCO following HKMTI-1–005 treatment is also an intriguing finding; inhibiting MARCO reprogrammes macrophages to acquire an antitumor phenotype, inhibiting tumor cell growth." (PMID 35131874, 2022). "Previous studies demonstrated that MARCO was specifically expressed by macrophages and mediated the clearance of tumor cells." (PMID 36428599, 2022). "MARCO is closely associated with metastasis driving gene signatures for epithelial‐mesenchymal‐transition (EMT), and targeted blocking of MARCO expression can effectively inhibit tumor metastasis." (PMID 34914196, 2022). "We previously reported that using antibodies against MARCO represents an effective immunotherapy in mice, reducing tumor growth and blocking metastasis in several cancer models." (PMID 36310582, 2022). "We have previously reported that targeting MARCO-expressing macrophages in murine cancer models reduced tumor growth and impaired metastasis." (PMID 36310582, 2022). "We observed that MARCO+ myeloid cells were primarily located in the tumor areas, while T and NK cells were present but mostly excluded from the tumor areas." (PMID 36310582, 2022). "Immunohistochemical analyses of tissues from a cohort of PDAC patients confirmed a high prevalence of MARCO-positive cells in the tumor stroma that also co-expressed the pan-macrophage marker CD68 in the majority of investigated specimens (n = 10)." (PMID 36310582, 2022). "In preclinical studies, anti-MARCO antibodies have been reported to inhibit tumor growth and metastasis in 4T1 mammary carcinoma and B16 melanoma mouse models." (PMID 35978372, 2022). "These suppressive myeloid cells expressed high levels of MARCO activated by tumor derived IL-10 that was induced via the transcription factor STAT3." (PMID 36310582, 2022). "Noteworthily, CD163 and MARCO expression as well as the combined expression of CD163 and MARCO in tumor tissues were also correlated with DFS and OS." (PMID 34778091, 2021). "MARCO, which becomes upregulated upon IL-37-induced M2 polarization is highly expressed on tumor-promoting macrophages and represents a therapeutic target for repolarization." (PMID 33924237, 2021).